OR1F2P (olfactory receptor family 1 subfamily F member 2 pseudogene)
Description:
Odorant receptor.
Synonyms: OR1F2; OLFMF2; OR16-3; OR1F11; OR1F3P; hg91
Gene: Unprocessed pseudogene on chromosome 16 (3,215,611 to 3,216,543, forward strand). Ensembl gene ENSG00000203581.
Subcellular location: Cell membrane